CASP8 (caspase 8)
Diseases named in the same sentence as CASP8 in open-access papers (continued):
Sharing a sentence is not in itself a finding about the gene and the disease.
ovarian carcinoma (continued). "Specific methylation was found in cervical cancer (including CDH1, DAPK, MGMT and MINT2), endometrial cancer (CASP8, CDH13, hMLH1 and p73), and ovarian cancer (BRCA1, p14, p15, RIZ1 and TMS1)." (PMID 16928264, 2006). "Caspase-8 expression is frequently dysregulated in ovarian cancer, leading to a discrepancy between its apoptotic and non-apoptotic functions in the tumor and the surrounding environment." (PMID 40674382, 2025). "Interestingly, BITC inhibited Bcl-2 expression and up-regulated the expression of caspase-3, caspase-8, c-PARP, and Bax, seemingly via activation of JNK1/2/p38 and inhibition of ERK1/2 and Akt signaling in ovarian cancer cells." (PMID 37190316, 2023). "Our investigation centered on elucidating the relationship between the migratory and invasive behaviors of ovarian cancer cells, considering the presence or absence of Caspase-8 expression." (PMID 38201534, 2023). "Related to this, Cisplatin and paclitaxel-resistant ovarian cancer cells treated with ixabepilone exhibit increased expression of death receptors DR4 and DR5, along with increased APO-2L/TRAIL-induced caspase 8, indicating activation via the extrinsic apoptosis pathway." (PMID 37047035, 2023). "There were no studies on the evaluation of caspase-8 serum levels in women with ovarian cancer, but the expression of this enzyme in patients with ovarian cancer was evaluated." (PMID 33919909, 2021). "Concomitantly, our previously published data have shown that treatment of human ovarian cancer cell lines A-2780 and SKOV-3 with DMU-214 resulted in the up-regulated activity of caspase-8, which was accompanied by the induction of the receptor-mediated apoptosis pathway." (PMID 34201116, 2021). "Abnormal expression of this enzyme in ovarian cancer leads to an imbalance between apoptotic and non-apoptotic functions of caspase-8, not only in the primary tumor, but also in the surrounding environment." (PMID 33919909, 2021). "Substantial reduce in cell viability was detected in both ovarian cancer cell lines by AUY922, and apoptosis was evidenced by caspase 8, and PARP cleavage, a significant increase in caspase 3/7 activity, and a dramatic increase in apoptotic cells compared with matched vehicle-treated cells." (PMID 21962244, 2011). "We have previously demonstrated that TRAIL-induced apoptosis was inhibited by the presence of ascites in ovarian cancer cell lines CaOV3 and OVCAR3 as a consequence of Akt activation and up-regulation of c-FLIPS, an inhibitor of TRAIL-induced caspase-8 activation." (PMID 20157422, 2010). "Furthermore, PEITC-mediated apoptosis induction was validated by increased activation of caspase-3, caspase-8, and caspase-9, and enhanced expression of Bax and c- PARP, while a significant reduction was noted in the expression of Bcl-2 in PEITC-exposed ovarian cancer cells." (PMID 37190316, 2023). "Importantly, clinical ovary cancer sample analysis consistently validates the relevance of PCBP1 expression to both p62/SQSTM1 and caspase-8 to overall survival, and indicates PCBP1 may be a master player to repress tumor initiation." (PMID 32922440, 2020). "Moreover, the lack of Caspase-8 alters transcriptional regulation in ovarian cancer cells." (PMID 38201534, 2023). "Therefore, we performed methylation analysis of 51 PYAGs and showed that AIM2, CASP1, CASP8, GSDMC and NLRP6 exhibited hypomethylation in ovarian cancer, which may provide a new theory to explore the methylation of above five genes to improve potential antitumor efficacy of OC." (PMID 36707884, 2023). "Along these lines, activation of caspase 3, caspase 8, and caspase 9 was induced by SW IV-134, but not by SW43 in different ovarian cancer cell lines." (PMID 24602489, 2014).
hepatocellular carcinoma (62 papers, 2003 to 2025). A malignant tumor that arises from hepatocytes. "High levels of Caspase-8 are associated with poor prognosis in patients with glioma, hepatocellular carcinoma and pancreatic cancer." (PMID 37444381, 2023). "Indeed, in some human tumors, such as head and neck squamous carcinomas or hepatocellular carcinomas, initiator caspase-8 is often mutated or deleted." (PMID 35409093, 2022). "It has been documented that CASP8 expression is elevated in breast and pancreatic cancer cells and correlates with poor prognosis in patients with hepatocellular carcinoma." (PMID 40149637, 2025). "In hepatocellular carcinoma, early- versus late-stage tumors show divergent caspase-8 responses, reflecting TME plasticity." (PMID 41291696, 2025). "Luteolin also promotes apoptosis in SMMC-7721 hepatocellular carcinoma cells by upregulating caspase-8 and downregulating BCL2 protein and mRNA levels." (PMID 40066127, 2024). "On the other hand, caspase-8 inhibitors blocked the apoptosis process in the human hepatoma cell line." (PMID 38672279, 2024). "This parallels with the findings on caspase-8 down-regulation in hepatocellular carcinoma, where methylation status of SP1 sites and nearby CpG dinucleotides in the promoter region were proposed to be a major regulator of caspase-8 expression." (PMID 36112666, 2022). "An in vitro study showed that the addition of caspase inhibitors, such as caspase-3 and caspase-8 inhibitors, can reverse the apoptosis induced by berberine in hepatoma." (PMID 33732240, 2021). "Caspase-8/10 silencing by promoter methylation disrupts the cycle of apoptosis in hepatocellular carcinoma, bladder cancer, small-cell lung carcinoma, glioblastoma, retinoblastoma, and neuroblastoma." (PMID 34199020, 2021). "Further, stigmasterol promotes the mitochondrial apoptosis signaling pathway, including the upregulation of caspase-8 and -9, in hepatoma." (PMID 32481565, 2020). "Vitexin compound 1 isolated from Vitex negundo killed hepatocellular carcinoma cells by the activation of caspase -8, -9 and -3." (PMID 31870094, 2019). "One puzzling issue arises from the observation that Caspase-8 expression is retained and even aberrantly overexpressed in some tumors, including hepatocellular carcinoma and glioblastoma." (PMID 30501030, 2018). "Using as model system hepatocellular carcinoma cells, the authors demonstrate that Caspase-8 expression is required for the phosphorylation of H2AX in response to DNA damage induction, which is important to initiate DNA repair." (PMID 30501030, 2018). "Knock down of UCA1 in HBx-expressing hepatic and hepatoma cells resulted in markedly increased apoptotic cells by elevating the cleaved caspase-3 and caspase-8." (PMID 27009634, 2016). "In hepatocellular carcinoma cells, TM strongly enhanced the activation of caspase-3, caspase-8, and caspase-9." (PMID 28018916, 2016). "In contrast, some studies demonstrated that MTX-induced apoptosis is mediated through the caspase-8/-3 cascade pathway in breast cancer, hepatoma and leukemia cells." (PMID 24969544, 2014). "In this study we assessed the expression of TRAIL receptors, caspase-8, Bcl-xL and Mcl-1 in 157 patients with hepatocellular carcinoma and normal liver tissue using tissue microarrays, and correlated the expression with clinico-pathological parameters." (PMID 24209510, 2013). "Our study found that, matrine induced both autophagy and apoptosis in hepatoma cells, and inhibition of autophagy enhanced matrine-induced apoptosis, which is related to the activity of caspase-8, -9, -3." (PMID 24287900, 2013). "A clear example comes from hepatocellular carcinoma, where caspase-8 supports apoptotic clearance and suppresses initiation in early stages, but in advanced tumors its activation fuels compensatory proliferation and microenvironmental remodeling that accelerate progression." (PMID 41291696, 2025).
hepatocellular carcinoma (continued). "Similarly, studies conducted in the human hepatoma (hepatocellular carcinoma) cell line Huh7 showed that part of the early response to TGF-β was an increase in the activity of caspase-8, followed by the activation of caspase-9 and caspase-3." (PMID 38672279, 2024). "RIPK1 leads to excessive activation of Caspase-8 and promotes hepatocellular carcinoma progression." (PMID 36110223, 2022). "Moreover, α- and γ-tocotrienol induced the apoptosis of rat hepatoma dRLh-84 cells via DNA fragmentation, as well as the activation of caspase-3 and caspase-8." (PMID 36139518, 2022). "In line with human evidence, deletion of both TRAF2 and RIP1 in liver parenchymal cells (LPC) leads to spontaneous development of hepatocellular carcinoma, which results from extensive hepatocyte apoptosis due to hyperactivation of caspase-8 but impaired NF-κB activation induced by TNFα." (PMID 30294322, 2018). "Based on these previous literatures, we searched several online tools for candidate miRNAs that might target caspase 3 and/or caspase 8 to inhibit their expression in TRAIL-resistant hepatocellular carcinoma cell lines, HepG2R and Bel-7402R." (PMID 29476051, 2018). "In addition, Src inhibition is associated with increased caspase-8 cleavage, which contributes to increased apoptosis in TRAIL resistant hepatic carcinoma cells." (PMID 26320171, 2015). "In a previous study, UDCA could also increase caspase-3, caspase-8 and caspase-9 activities to induce apoptosis in HepG2 hepatocellular carcinoma cells." (PMID 25951128, 2015). "Moreover, it was demonstrated that ginsenoside (Rh2) induces apoptosis of human hepatoma cells via Bax/Bak and caspase-9/caspase-8 activation." (PMID 24981420, 2014). "In contrast, DNA methylation-mediated downregulation of caspase-8 is correlated with reduced apoptosis in glioma, hepatocellular carcinoma (HCC), bladder cancer and small-cell lung carcinoma." (PMID 40555741, 2025). "Looking at hepatocellular carcinoma (HCC), propofol also efficiently inhibited the growth of HCC cells and activated both caspase-8 and caspase-9, suggesting that both intrinsic and extrinsic pathways induce apoptosis." (PMID 36143832, 2022). "The finding that Caspase-8 expression is retained in many tumors, including hepatocellular carcinoma and some glioblastoma, suggests that in these contexts its apoptotic activity may be switch off and its function rewired, as described in the previous section, to sustain tumor growth." (PMID 30501030, 2018). "To gain further insight into the regulation of apoptosis in hepatocellular carcinoma (HCC), we investigated the TRAIL pathway and the regulators of apoptosis caspase-8, Bcl-xL and Mcl-1 in patients with HCC regarding patient survival." (PMID 24209510, 2013). "ILC3s were able to directly kill both hepatocellular carcinoma and melanoma tumor cells expressing cell-death receptor TRAILR2, through the activation of Caspase-8 in target cells." (PMID 35300331, 2022). "DNMT1 and DNMT3b silencing was shown to sensitize human hepatoma cells via upregulation of DR5 and caspase-8." (PMID 34199020, 2021). "In hepatoma cells, primary glioma and esophageal squamous cell carcinoma cells DISC analysis revealed that bortezomib enhanced the recruitment of TRAIL-receptors, FADD and caspase-8 upon rhTRAIL stimulation." (PMID 41180258, 2025). "To generalise our findings, we treated five commonly used cancer cell lines of colorectal (DLD1, HCT116 and SW480), breast (MDA231) and hepatocellular carcinoma (SNU387) origin with oxaliplatin to activate caspase-9, or death-receptor ligand TRAIL to activate caspase-8,-initiated apoptosis." (PMID 38272916, 2024). "Additionally, it was found to induce apoptosis in hepatocellular carcinoma (HCC) cells (HepG2) by promoting the release of cytochrome c into the cytoplasm, thereby activating caspase-8, caspase-9, and caspase-3." (PMID 39770441, 2024).
hepatocellular carcinoma (continued). "Consequently, A20 leads to an inhibition of caspase 8 activation and subsequently to resistance to TRAIL-induced apoptosis in glioblastoma or hepatocellular carcinoma cells." (PMID 36596765, 2023). "In hepatoma HepG2 cells, TSAIII treatment is reported to activate cleaved-caspase-3, caspase-8, and caspase-9, increase the expression of Mcl-1 and Bcl-2, and induce the release of cytochrome C, suggesting that TSAIII induces caspase-dependent and mitochondrial-mediated apoptosis." (PMID 36611961, 2022). "It was found that protopine treatment enhanced the activities of caspase-3 and caspase-9 but not caspase-8 in a dose-dependent manner in liver carcinoma cells." (PMID 34315493, 2021). "Methylation-induced regulation of caspase-8 expression has also been described in SCLC and hepatocellular carcinomas (HCC)." (PMID 31248188, 2019). "We analyzed 157 hepatocellular carcinoma patients who underwent partial liver resection or orthotopic liver transplantation and healthy control liver tissue using immunohistochemistry on tissue microarrays for the expression of TRAIL-R1 to TRAIL-R4, caspase-8, Bcl-xL and Mcl-1." (PMID 24209510, 2013). "Similarly, autophagy protects hepatoma cells from TNF-induced cytotoxicity by blocking caspase-8 activation and the mitochondrial death pathway, while its inhibition elevates TNF levels and caspase-8 activity, suggesting therapeutic potential in TNF-mediated tissue damage." (PMID 41254398, 2025). "In the present study, we demonstrated a decrease in caspase 3 and caspase 8 mRNA expression and protein levels in TRAIL-resistant hepatocellular carcinoma cells, suggesting that rescue of caspase 3 and caspase 8 levels may improve TRAIL-resistance in hepatocellular carcinoma." (PMID 29476051, 2018).
glioma (58 papers, 2008 to 2025). A benign or malignant brain and spinal cord tumor that arises from glial cells (astrocytes, oligodendrocytes, ependymal cells). "ConBr, a lectin extracted from the Canavalia brasiliensis seeds, induced autophagy and cell death dependent on caspase 8, and its cytotoxicity on CG glioma cells was associated with MAPKS and Akt pathways modulation." (PMID 37259433, 2023). "Then, from the K-M curves, an association was obtained between CASP8 expression and the poor prognosis of glioma patients." (PMID 36466844, 2022). "Theoretically, an altered ratio of Bcl-2/Bax causes downstream activation of caspase cascades (such as caspase 8), ultimately leading to the activation of cleaved caspase 348–50, which was observed in glioma cells after treatment with α-m-Dox/M." (PMID 33116114, 2020). "Finally, the necroptosis suppressor CASP8 exhibited a high expression in glioma and was associated with poor prognosis." (PMID 36466844, 2022). "In the case of glioma, knocking down Caspase-8 resulted in weakened Bufalin-induced apoptosis and a significant increase in cell necrosis." (PMID 37762285, 2023). "Multiple molecular aberrations contribute to TRAlL-resistance of glioma, such as lower expression of caspase-8, overexpression of c-FLIP, Bcl-2 and Bcl-xL or loss or structural alterations of TRAIL-R1, TRAIL-R2, Apaf-1, Smac and Bid." (PMID 37158962, 2023). "In summary, Bufalin can trigger both apoptosis and necrosis in glioma, and their manifestation is closely linked to the status of TNF-α, Caspase-8, and RIPK1 proteins." (PMID 37762285, 2023). "Subsequent experiments were performed in human glioma cell lines and patients' tissue specimens to verify the bioinformatic analytic findings about CASP8." (PMID 36466844, 2022). "Given the key role of CASP8 in regulating cell death process and its high expression in glioma, we further explored the biological function of CASP8 in glioma at mRNA level, based on the TCGA database." (PMID 36466844, 2022). "Both IFNGR2 and CASP8 represented the common intersection genes as revealed by the venn plot after combining the DEGs between glioma and normal brain tissues, NRS gene set, and important survival genes from the random forest." (PMID 36466844, 2022). "PEA15 is a caspase-8 inhibitor and is upregulated in various glioma cell lines and correlates with the resistance of human glioma cells to anticancer drugs, such as TRAIL." (PMID 35328780, 2022). "We first detected the expression of CASP8 in glioma cell lines using Western blot analysis and found that CASP8 expression was highest in LN299 cells." (PMID 35296768, 2022). "They showed that an ethanolic extract of propolis induced apoptosis in C6 glioma cells by activating the caspase cascade pathway, increasing caspase-8, -9, and -3 expression levels." (PMID 35883797, 2022). "CASP8 high expression seems to be one of the mechanism by which glioma escapes necroptosis and therefore it represents a potential biomarker for glioma prognosis." (PMID 36466844, 2022). "And then, CASP8 expression in microglia was verified by IFH assay in glioma patients’ tissues, and we found a significant colocalization of CASP8 and microglia cell marker CD11B." (PMID 36466844, 2022). "We firstly detected the expression of CASP8 in glioma cell lines using the Western blot analysis, and found CASP8 is the most highly expressed in LN299 cell." (PMID 35069683, 2021). "We selected the CASP8 to validate the molecular function because: First, the significantly high expression of CASP8 is found between glioma and normal control." (PMID 35069683, 2021). "Similar to our result, the combination treatment with PAC and ATRA was shown to promote the apoptosis of U87MG glioma cells through the inactivation of Bcl-2 and upregulation of activated caspase-8 expression." (PMID 34660779, 2021).